AZGP1 (alpha-2-glycoprotein 1, zinc-binding)
Diseases named in the same sentence as AZGP1 in open-access papers (continued):
Sharing a sentence is not in itself a finding about the gene and the disease.
metabolic syndrome (22 papers, 2012 to 2025). A cluster of metabolic risk factors for CARDIOVASCULAR DISEASES and TYPE 2 DIABETES MELLITUS. "According to our findings, the AZGP1 gene-enriched pathway in the skeletal muscle is directly related to dyslipidemia, inflammatory response mediated by TNF-alpha and IL-1b, and metabolic diseases." (PMID 35804531, 2022). "CCL3 and AZGP1 showed two-fold higher and lower expression, respectively, in women with metabolic syndrome compared to women without metabolic syndrome." (PMID 23028366, 2012).
diabetes (19 papers, 2011 to 2024). "In the AKI cohort we observed an association between initial AZGP1 levels and pre-existing comorbidities, such as diabetes, hypertension and coronary heart disease." (PMID 23849457, 2013). "Using Metascape, we found that 4 genes (AZGP1, DLK1, GCKR and NEGR1) are linked to diabetes." (PMID 38184718, 2024). "AZGP1 has also been shown to be increased in diabetes and diabetic nephropathy." (PMID 22091387, 2011). "When we analyzed the correlation between the clinical and pathological characteristics of ICC patients and AZGP1 expression, there were no significant with any of the following factors: age, sex, tumor stage, diabetes, tumor size and tumor differentiation." (PMID 37669935, 2023).
colorectal cancer (14 papers, 2014 to 2025). A primary or metastatic malignant neoplasm that affects the colon or rectum. "MIIP down-regulation in colorectal cancer cells led to an increase in AZGP1 N-glycosylation and subsequent aberrant secretion of AZGP1, which, in turn, induced peri-cancerous WAT browning and lipolysis via the cAMP–PKA pathway." (PMID 38245780, 2024). "AZGP1 is a useful diagnostic biomarker found in the tissues and serum of Chinese CRC patients and it promotes epithelial-mesenchymal transition (EMT) in colorectal cancer via the filamin A-mediated focal adhesion pathway." (PMID 34698109, 2021). "AZGP1 has been reported to inhibit colorectal cancer progression via the mTOR signaling pathway and has also been shown to suppress the progression of malignant soft-tissue sarcoma cells." (PMID 33834191, 2021). "We previously found that up-regulated AZGP1 promotes proliferation, migration and invasion in colorectal cancer cell line, here we elucidated the mechanism of AZGP1 in regulating metastasis." (PMID 31632499, 2019). "Rescue experiment showed that over-expressed AZGP1 promoted the migration of colorectal cancer, but it can be reversed when the PAK2 inhibitors are added." (PMID 31632499, 2019). "To figure out the liver metastasis of colorectal cancer, we obtained abnormal expressed genes through 6 patients without liver metastasis and 5 patients with liver metastasis by the HG-U133 microarray (Affymetrix), among these, AZGP1 was one of the most significant highly expressed molecules." (PMID 31632499, 2019). "circNOLC1 interacting with AZGP1 to activate mTOR/SREBP1 signaling, or sponging miR‐212‐5p to upregulate c‐Met expression, both of which can further induce G6PD to activate oxidative pentose phosphate pathway in colorectal cancer liver metastasis." (PMID 37870214, 2023). "In this article, we found that AZGP1 was also highly expressed in colorectal cancer tissues with liver metastasis relative to those without metastasis, and abundant expression of AZGP1 was associated with poor prognosis, also, AZGP1 down regulation prevented cell metastasis in vivo and in vitro." (PMID 31632499, 2019).
pancreatic cancer (12 papers, 2012 to 2026). "Similarly, the low mRNA/protein expression of AZGP1 is associated with disease progression and poor survival in pancreatic cancer." (PMID 36052234, 2022). "Researchers have identified AZGP1 as a tumor suppressor in several types of cancer, including hepatocellular carcinoma, pancreatic cancer and gastric cancer." (PMID 37669935, 2023). "Our data also shows down regulation of tumour suppressor genes AZGP1, EGLN1 and GNMT of which AZGP1, a Zinc α2-glycoprotein which when silenced was shown to increase invasiveness of pancreatic cancer by induction of mesenchymal transition." (PMID 35854233, 2022). "AZGP1 has also been determined to play an important role in the TGF-β1-induced epithelial-to-mesenchymal transition (EMT) in pancreatic cancer and hepatocellular carcinoma." (PMID 31632499, 2019). "AZGP1 acts as a tumour suppressor in breast, prostate, gastric, liver and pancreatic cancer." (PMID 38183356, 2024). "In addition, it has been shown that AZGP1 acts as a novel tumor suppressor in pancreatic cancer." (PMID 23935945, 2013). "We found that, in the case of pancreatic cancer also, treatment with EHMT2 inhibitors (A366 and UNC0642) resulted in increased NK cell-mediated cytotoxicity, AZGP1 upregulation, and TGF-β1 downregulation." (PMID 41366520, 2026). "Most downregulated RBPs include PAIP2B, SIDT2, PDCD4, AZGP1, and RNASE1, among which we report for the first-time involvement of PAIP2B, SIDT2, PDCD4, and RNASE1 in pancreatic cancer." (PMID 34912796, 2021). "AZGP1 as a cancer suppressor inhibited cell proliferation, migration, and invasion via TGF-β and PTEN/Akt signaling pathways in pancreatic cancer and hepatocellular carcinoma." (PMID 33505420, 2020).
gastric cancer (10 papers, 2013 to 2026). A primary or metastatic malignant neoplasm involving the stomach. "Univariate analyses showed that the decreased expression of AZGP1 in gastric cancer tissues was significantly associated with the overall survival rate and the 5-year survival rate." (PMID 23935945, 2013). "In addition, AZGP1 loss has been found to be a predictor of poor outcomes in several malignancies including gastric cancer, esophageal squamous cell carcinoma, liver cancer, and bladder cancer." (PMID 38659028, 2024). "Additionally, down-regulation of AZGP1 was also associated with poor prognosis in liver and gastric cancers." (PMID 35433689, 2022). "Multivariate analysis demonstrated that AZGP1 expression, together with some traditional prognostic factors such as tumor location, T stage and N stage, were independent risk factors in the prognosis of gastric cancer patients." (PMID 23935945, 2013). "In addition, we discovered that decreased expression of AZGP1 was associated with poorly differentiated adenocarcinomas (G3 vs. G1/G2), indicating that AZGP1 may induce the differentiation of gastric cancer." (PMID 23935945, 2013). "In conclusion, we first investigated the expression levels and prognostic value of AZGP1 in primary gastric cancers in this study." (PMID 23935945, 2013). "In order to confirm the molecular biological findings and investigate the clinicopathological the prognostic roles of AZGP1 expression, we performed immunohistochemical analysis in 248 paraffin-embedded gastric cancer sections." (PMID 23935945, 2013). "In this study, we investigated the expression levels and prognostic value of AZGP1 in primary gastric cancers." (PMID 23935945, 2013). "Relationship between AZGP1 expression and clinicopathologic features of patients with gastric cancer." (PMID 23935945, 2013). "To further validate this reduction of AZGP1 expression in primary gastric cancer, we performed immunohistochemical analysis with a rabbit anti-hAZGP1 antibody." (PMID 23935945, 2013). "We observed lower expression of AZGP1 immunostaining in proximal or total gastric cancer compared with distant gastric cancer tissues." (PMID 23935945, 2013). "In this study, we analyzed the AZGP1 expression level in gastric cancers by using real-time quantitative RT-PCR (qRT-PCR), western blotting and immunohistochemistry." (PMID 23935945, 2013). "The AZGP1 protein levels in the resected gastric cancer samples were determined by western blotting." (PMID 23935945, 2013). "Among the 248 gastric cancer samples, 117 (47.2%) showed high AZGP1 expression (AZGP1++ or AZGP1+++), whereas the remaining 131 cases (52.8%) displayed low AZGP1 expression (AZGP1- or AZGP1+)." (PMID 23935945, 2013). "However, in gastric cancer, overexpression of AZGP1 has been reported to accelerate apoptosis and inhibit growth through modulation of the mTOR/PTEN signaling pathway." (PMID 38659028, 2024). "The functional role and mechanisms of AZGP1 in gastric cancer need further investigation." (PMID 23935945, 2013). "Furthermore, we identified the relationship between AZGP1 expression and the clinicopathological features of gastric cancer, and we evaluated the prognostic value of AZGP1 expression for the post-resection survival of gastric cancer patients." (PMID 23935945, 2013). "Similarly, the lncRNA LINC01094, which is associated with tumour risk, can specifically target the AZGP1 gene, thereby activating the PTEN/AKT signalling pathway, which significantly promotes the abnormal proliferation and distant metastasis of gastric cancer cells." (PMID 41299664, 2025). "The transcriptional levels of AZGP1 were determined with qRT-PCR assays using 35 pairs of resected specimens (tumor tissue samples and matched adjacent non-tumor tissue samples) from gastric cancer patients." (PMID 23935945, 2013). "However, so far the expression status of AZGP1 and prognostic value of this protein in primary gastric cancers have not been reported." (PMID 23935945, 2013).
hepatocellular carcinoma (10 papers, 2012 to 2024). A malignant tumor that arises from hepatocytes. "Decreased expression of AZGP1 is associated with a poor prognosis in primary gastric cancer and hepatocellular carcinoma 9,10." (PMID 31632499, 2019). "In hepatocellular carcinoma, the underlying molecular mechanism by which AZGP1 inhibits cell migration and invasion is regulating the PTEN/Akt and CD44 pathways." (PMID 31632499, 2019). "Histone deacetylation has also been reported to regulate the expression of AZGP1 in hepatocellular carcinoma." (PMID 37669935, 2023). "lncRNA LINC00844, a highly expressed lncRNA in hepatocellular carcinoma, was shown to be a tumor inhibitor within hepatocellular carcinoma and suppress the metastasis of tumor cells via targeting AZGP1." (PMID 34336002, 2021). "AZGP1 participates in metabolic processes such as lipolysis and glucose transport, and acts as a tumor suppressor in malignant tumors such as pancreatic ductal adenocarcinoma and hepatocellular carcinoma." (PMID 37583433, 2023). "However, AZGP1 expression in hepatocellular carcinoma (HCC) and its significance remain largely unknown." (PMID 22625427, 2012).
lung carcinoma (10 papers, 2018 to 2026). "Salivary proteins with high specificity and sensitivity to identify lung cancer include calprotectin, AZGP1, and HP." (PMID 38202898, 2023). "LINC01426 contributes to clear cell renal cell carcinoma progression by modulating CTBP1/miR-423-5p/FOXM1 axis via interacting with IGF2BP1, and to lung cancer progression via AZGP1 and predicts poor prognosis in patients with LUAD." (PMID 35818395, 2022). "AZGP1 mRNA expression in human lung tissue has been found to correlate with the stage of lung cancer disease." (PMID 31122252, 2019). "It has been reported that patients with prostate or lung cancer with low AZGP1 levels had worse survival compared to those with high levels." (PMID 29357838, 2018). "Alpha‐2‐Glycoprotein 1, Zinc‐binding (AZGP1, ZAG) is a secreted protein that is synthesized by adipocytes and epithelial cells; it is downregulated in several malignancies such as breast, prostate, liver and lung cancers." (PMID 38183356, 2024). "Furthermore, overexpression of S100A13 (P = 7.29e-4, t test), AZGP1 (P = 6.31e-4, t test), and PPT1 (P = 1.18e-4, t test), significantly increased the proliferation of lung cancer H1299 cells." (PMID 35027529, 2022).
chronic kidney disease (9 papers, 2013 to 2022). Impairment of the renal function secondary to chronic kidney damage persisting for three or more months. "End stage renal disease has been shown to be associated with increased AZGP1 levels." (PMID 23849457, 2013). "In this study, serum AZGP1 levels were measured in acute and chronic kidney disease to test for a correlation to renal function and other clinical parameters." (PMID 23849457, 2013). "Therefore, circulating AZGP1 significantly accumulates in patients with disrupted renal function and acute or chronic renal failure." (PMID 35054830, 2022). "Previous studies have shown increased circulating AZGP1 levels in patients with chronic kidney disease but AZGP1 has not been investigated in acute kidney injury (AKI)." (PMID 23849457, 2013). "Importantly, there is a discrepancy in reported effects of AZGP1 on CVD between patients with and without chronic kidney disease (CKD)." (PMID 34291094, 2021).
polycystic ovary syndrome (8 papers, 2016 to 2023). A disorder that manifests as multiple cysts on the ovaries. "Circulating AZGP1 has been linked to polycystic ovary syndrome (PCOS) and might be a significant adipokine in the onset and progression of PCOS." (PMID 35677823, 2022).
colon cancer (7 papers, 2014 to 2026). "We validated AZGP1 diagnostic value in serum by leave-one-out cross-validation, which showed that AZGP1 and the combination with traditional serum biomarkers were useful serum biomarkers of colon cancer in a Chinese population." (PMID 25561225, 2014). "We hypothesized that AZGP1 could be used as a diagnostic marker of colon cancer." (PMID 25561225, 2014). "AZGP1 was significantly upregulated at the transcriptional and posttranscriptional level in colon cancer tissues." (PMID 25561225, 2014). "We verified that serum concentration of AZGP1 was higher in 120 colon cancer patients compared with 40 healthy controls by ELISA (p < 0.001)." (PMID 25561225, 2014). "Analyzing “The Cancer Genome Atlas” data, we found that in colon cancer AZGP1 gene expression was upregulated at transcriptional level." (PMID 25561225, 2014). "Taken together, our study is the first comprehensive evaluation of AZGP1 variation at the mRNA and protein level in human colon cancer." (PMID 25561225, 2014). "The expression levels of AZGP1 mRNA and protein in colon cancer tissues were higher than those in matched normal mucosa, suggesting that AZGP1 was upregulated at the transcriptional and posttranscriptional level." (PMID 25561225, 2014). "Moreover, AZGP1 was significantly upregulated in a tissue microarray containing 190 samples of primary colon cancer tissue compared with normal colonic tissue." (PMID 31632499, 2019). "Our study demonstrated AZGP1 could be a novel molecular marker and of significance in the diagnosis of colon cancer in Chinese population." (PMID 25561225, 2014). "We evaluated AZGP1 mRNA and protein expression in fresh colon cancer tissues by qPCR and WB." (PMID 25561225, 2014). "Our study demonstrated that AZGP1 is a potential serum marker of colon cancer that may be correlated with tumorigenesis." (PMID 25561225, 2014). "Here, we identified AZGP1 as a potential biomarker for colon cancer." (PMID 25561225, 2014). "Additionally, high serum concentrations of AZGP1 were detected in colon cancer patients, and the combination of AZGP1 with traditional serum biomarkers, CEA and CA19-9, resulted in a more accurate diagnostic result than the individual ones." (PMID 25561225, 2014). "To prove this hypothesis, we examined AZGP1 differential expression in colon cancer specimens and paired normal mucosa specimens by using quantitative real time polymerase chain reaction (PCR) and western blot (WB)." (PMID 25561225, 2014). "Additionally, the combination of AZGP1 with the traditional serum biomarkers CEA and CA19-9 could result in better diagnostic results in colon cancer." (PMID 31632499, 2019). "Further, we found that in tissue samples data and in serum samples data the AZGP1 expression level was positively correlated with AJCC clinical stage, the result indicating that colon cancer patients with higher AZGP1 expression levels were in significantly more advanced progression of the disease." (PMID 25561225, 2014).
coronary heart disease (5 papers, 2013 to 2022). "While serum AZGP1 correlated with CV disease and mortality in dialysis patients, there was an inverse relationship with atherosclerosis and coronary heart disease in non-dialysis patients." (PMID 34083628, 2021). "While higher AZGP1 levels were associated with reduced incidence of coronary heart disease and atherosclerosis in non-CKD patients, higher AZGP1 levels were shown to correlate positively with CVD in ESRD patients." (PMID 34291094, 2021).
acute kidney injury (4 papers, 2011 to 2024). Sudden and sustained deterioration of the kidney function characterized by decreased glomerular filtration rate, increased serum creatinine or oliguria. "Moreover, studies have shown that blood AZGP1 is significantly increased in patients with chronic hemodialysis and early acute kidney injury." (PMID 39337423, 2024). "Alteration of AZGP1 and LRG expression is predictive of acute kidney injury in postsurgical patients." (PMID 22091387, 2011). "So far, AZGP1 has not been investigated in the context of acute kidney injury (AKI)." (PMID 23849457, 2013).
epilepsy (4 papers, 2016 to 2025). A brain disorder characterized by episodes of abnormally increased neuronal discharge resulting in transient episodes of sensory or motor neurological dysfunction, or psychic dysfunction. "Recently, AZGP1 was found to be expressed in brain tissue and plays a role in several CNS diseases, such as epilepsy and Alzheimer’s disease." (PMID 38643150, 2024). "In our previous study, we found that both ZAG protein and AZGP1 mRNA levels were significantly decreased in brain tissues of refractory TLE patients and pentylenetetrazol (PTZ)-kindled rats, but the role of ZAG in epilepsy and seizure is still unclear." (PMID 29566716, 2018).
Hepatic steatosis (4 papers, 2019 to 2025). Steatosis is a term used to denote lipid accumulation within hepatocytes. "Further, liver-secreted AFM and AZGP1 correlate with circulating levels, adequately reflecting changes in liver secretion in MASH and for liver-secreted AFM and liver steatosis." (PMID 40250425, 2025).
liver cancer (4 papers, 2018 to 2026). An epithelial or non-epithelial malignant neoplasm that arises from the liver. "In liver cancer, AZGP1 has been found to inhibit the TGF-β1-ERK2 pathway, PTEN/Akt pathway, the CD44 signaling pathway, and epithelial-to-mesenchymal transition (EMT)." (PMID 38659028, 2024).
non-alcoholic fatty liver disease (4 papers, 2019 to 2025). "By negatively regulating TNF-α, AZGP1 reduces the severity of Nonalcoholic fatty liver disease (NAFLD) by lowering inflammation, speeding lipolysis, boosting proliferation, and minimizing apoptosis." (PMID 35677823, 2022). "In the liver, different studies showed a significant impact of AZGP1 on fatty acid metabolism, such as accelerated lipolysis and reduced inflammation in non-alcoholic fatty liver disease (NAFLD)." (PMID 35054830, 2022).
breast tumor (3 papers, 2008 to 2023). "The levels of AZGP1 have been found to be higher in well differentiated than in moderate or poorly differentiated breast tumors." (PMID 18328103, 2008).
cholangiocarcinoma (3 papers, 2024 to 2025). A carcinoma that arises from the intrahepatic biliary tree (intrahepatic cholangiocarcinoma) or from the junction, or adjacent to the junction, of the right and left hepatic ducts (hilar cholangiocarcinoma). "Our findings reveal that soluble AZGP1 acts as a predictive biomarker for 5-FU efficacy in cholangiocarcinoma and exerts pro-apoptotic and immunomodulatory functions via interaction with PD-L1." (PMID 41013181, 2025). "A previous study on cholangiocarcinoma (CCA) identified TRIM25 as a negative regulator of AZGP1 and suggested that pathologically reduced AZGP1 may result from increased TRIM25 levels, since patients suffering from CCA were nearly deficient in AZGP1, but showed a high amount of TRIM25." (PMID 39851496, 2025).